SPESP1 (sperm equatorial segment protein 1)
Description:
Involved in fertilization ability of sperm.
Synonyms: SP-ESP; ESP
Tractability: Antibody: UniProt predicts a signal peptide or a membrane-spanning region.
Gene: Protein-coding gene on chromosome 15 (68,818,221 to 68,946,811, forward strand). Ensembl gene ENSG00000258484.
Subcellular location: Cytoplasmic vesicle, secretory vesicle, acrosome
Subcellular location (Human Protein Atlas): Acrosome; Equatorial segment; Cytokinetic bridge; Microtubules; Mitotic spindle; Predicted to be secreted
Gene Ontology:
Biological process: acrosome reaction; fertilization; fusion of sperm to egg plasma membrane involved in single fertilization; sperm-egg recognition
Cellular component: acrosomal vesicle
Genetic constraint (gnomAD): Loss-of-function variants: 4 observed, 3.03 expected, observed/expected ratio (o/e) 1.32, 90% interval 0.59 to 1.91. That is too few expected variants to judge how well the gene tolerates losing a copy. Missense variants: 393 observed, 428.95 expected, observed/expected ratio (o/e) 0.92, 90% interval 0.84 to 1. Synonymous variants: 138 observed, 158.76 expected, observed/expected ratio (o/e) 0.87, 90% interval 0.76 to 1.
Homologues: Orthologues: chimpanzee SPESP1 (99% identical), macaque SPESP1 (92% identical), rabbit SPESP1 (65% identical), dog SPESP1 (62% identical), pig SPESP1 (62% identical), rat Spesp1 (49% identical), mouse Spesp1 (48% identical).
Diseases named in the same sentence as SPESP1 in open-access papers:
SPESP1 is named in the same sentence as 11 diseases in open-access papers, as found by Europe PMC text mining. Sharing a sentence is not in itself a finding about the gene and the disease. The quoted sentences say what the papers report.
infertile (3 papers, 2016 to 2023). "Proteomic and immunofluorescence analyses verified that acrosome-related proteins, including acrosin-binding protein (ACRBP) and sperm equatorial segment protein 1 (SPESP1), were downregulated in infertile sperm." (PMID 34070710, 2021).
male infertility (3 papers, 2016 to 2021). The inability of the male to effect fertilization of an ovum after a specified period of unprotected intercourse. "Meanwhile, Spesp1 mutant mice have been shown to low sperm viability and male infertility." (PMID 32787870, 2020). "Moreover, a mouse model lacking Spesp1 shows male infertility but no defect in any somatic tissues, including skin, which argues in favor of testis‐specific roles (hence expression)." (PMID 33426787, 2021). "Collectively, these results indicated that these proteins AKAP4, ODF1, ODF2, GAPDHS, SPESP1, and ACTRT2 were significantly down-regulated after heat treatment of scrotum, suggesting that these proteins may serve as the biomarkers for scrotal heat treatment-induced male infertility." (PMID 32787870, 2020).
congenital heart disease (1 paper, 2024). A heart disease that is present at birth. "Moreover, SPESP1 is hypermethylated in congenital heart disease and is implied as a new biomarker and potential intervention target for congenital heart disease." (PMID 38764260, 2024).
polycystic ovary syndrome (1 paper, 2022). A disorder that manifests as multiple cysts on the ovaries. "Two genes, the fem-1 homolog B (FEM1B) and sperm equatorial segment protein 1 (SPESP1) on BTA10, were reported to be involved in polycystic ovary syndrome in humans and required for fully fertile sperm in mice, respectively." (PMID 35484513, 2022).
skin cancer (1 paper, 2021). "Taken together, the data support the notion that SPESP1 is a testicular protein that accumulates in a substantial fraction of skin cancer samples." (PMID 33426787, 2021).
skin tumors (1 paper, 2021). "Next, we employed a commercial tissue microarray (TMA) covering 84 benign and malign skin tumors, 12 samples from other tumors (breast, ear, fibrous tissue, parotid gland, vulva), and four normal skin samples to analyze SPESP1's staining pattern (SK803a)." (PMID 33426787, 2021).
cancer (1 paper, 2021). A tumor composed of atypical neoplastic, often pleomorphic cells that invade other tissues. "In summary, misexpression of SPESP1 may contribute to genetic instability and altered growth properties in somatic cancer cells." (PMID 33426787, 2021).
tumour diseases (1 paper, 2024). "While previous studies have linked SPESP1 to the growth and development of tumour diseases, there remains a limited understanding of the functional roles and underlying mechanisms of SPESP1." (PMID 38764260, 2024).
SPESP1 also shares sentences with these, for which no sentence is quoted: channelopathies (1 paper); colorectal cancer (1); gastric cancer (1).